NDRG2 (NDRG family member 2)
Diseases named in the same sentence as NDRG2 in open-access papers (continued):
Sharing a sentence is not in itself a finding about the gene and the disease.
tumor (continued). "Furthermore, the expression of NDRG2 is closely related to tumor prognosis, which is associated with cancer metastasis inhibition and therapeutic outcome." (PMID 34685629, 2021). "NDRG2 expression has been linked with tumor grade and tumor recurrence." (PMID 31485792, 2019). "To further explore whether the loss of NDRG2 in tumor-infiltrating macrophages could contribute to the decreased tumor metastasis in Ndrg2−/− mice, we transplanted bone marrow (BM) from syngeneic WT or Ndrg2−/− mice into lethally irradiated WT recipients." (PMID 29445150, 2018). "The aim of this study was to determinate aberrant promoter methylation and mRNA expression of NDRG2 in PAs and to evaluate the associations between the methylation profile of gene, mRNA expression, patients’ clinical characteristics and tumor invasiveness and recurrence." (PMID 28390436, 2017). "NDRG2 is associated with tumor incidence, progression, and metastasis." (PMID 26506239, 2016). "Collectively, these data indicate that the expression of Ndrg2 is significantly reduced at mRNA and protein levels in GC cells, and loss of Ndrg2 expression may associate with tumor progression and metastasis." (PMID 25823664, 2015). "However, it was validated that NDRG2 can support liver metastasis of cancer by switching macrophage phenotype from M1-like tumor-associated macrophages (TAMs) to M2-like TAMs, suggesting that further investigations are necessary to unveil the precise function of NDRG2." (PMID 33435156, 2021). "Here, we established a cancer liver metastasis model in wild-type and Ndrg2 knockout (Ndrg2−/−) mice and found that the Ndrg2−/− liver microenvironment significantly suppressed the growth of liver colonies with infiltration of a higher proportion of M1-like tumor-associated macrophages (TAMs)." (PMID 29445150, 2018). "Furthermore, the loss of NDRG2 expression might play an important role in the progression of tumor development after HTLV-1 infection." (PMID 26269411, 2015). "Another study elucidated that NDRG2, as a tumor suppressor gene, is negatively regulated by lipid carrier protein 2 (LCN2) in CCA cells." (PMID 41513616, 2026). "KLF5 is upregulated in PDAC, and its downregulation was reported to inhibit PDAC cell proliferation and tumorigenesis in mice by increasing the expression of the tumor suppressor NDRG2 and reducing the activation of STAT5." (PMID 39972489, 2025). "Briefly, NDRG2 was elucidated to be a tumor suppressor gene in meningioma, while NDRG4 has a proto-oncogenic role in this cancer." (PMID 40378957, 2025). "Emerging evidence has also demonstrated that NDRG2 acts as a tumor suppressor and is involved in regulating proliferation, differentiation, apoptosis, and metastasis in various malignant tumors." (PMID 40378957, 2025). "In this latter study, it was revealed that, similar to NDRG1, NDRG2 mRNA and protein levels were increased in several tumor cell lines exposed to hypoxia." (PMID 40378957, 2025). "NDRG2 is a tumour suppressor gene that plays a role in cell differentiation, stress response, and the inhibition of cell proliferation." (PMID 41179304, 2025). "Nevertheless, there is increasing evidence supporting a role for NDRG2 as a tumor suppressor that reduces metastatic activity via MMP-2/9." (PMID 37450923, 2024). "While many studies have reported that these family members have tumor suppressive roles, recent studies have demonstrated that NDRGs, particularly NDRG1 and NDRG2, function as oncogenes, promoting tumor growth and metastasis." (PMID 38611020, 2024). "The downregulation of NDRG2 expression is involved in tumour progression through the aberrant phosphorylation of several important signalling molecules." (PMID 38474089, 2024). "In contrast to NDRG1, NDRG2 acts as a tumor suppressor, inhibiting proliferation and cell survival via regulations of MAPK/STAT3, cyclin-D1, β-catenin, NF-κB, E-cadherin, and other signaling pathways." (PMID 38611020, 2024).
tumor (continued). "In contrast to NDRG1, we found that NDRG2 expression was higher in normal samples than in tumor samples (p < 0.0001)." (PMID 38611020, 2024). "Since NDRG2 was originally known as a tumor suppressor, additional studies are needed to determine the role that Ser350 in NDRG2 plays in cancer metastasis." (PMID 39057063, 2024). "In HCC, the expression of NDRG2 is downregulated, which is consistent with our findings, and down-regulation of NDRG2 expression can significantly increase tumor angiogenesis via the VEGFA pathway." (PMID 38874512, 2024). "Recently, a tumour suppressor gene, NDRG2, has been identified that belongs to the downstream gene family of N-Myc." (PMID 37829798, 2023). "As a tumor suppressor, NDRG2 exerted critical roles in anti-proliferation, pro-apoptosis as well as in restraining invasion and metastasis in different cancers." (PMID 37373150, 2023). "NDRG2 is a tumor suppressor, that is, downregulated in a variety of malignancies and is associated with the tumor differentiation stage." (PMID 37745860, 2023). "Meanwhile, NDRG2 protein level is negatively correlated with the tumor stage and aggressive behavior, which can act as a biomarker of tumor progression and prognosis." (PMID 37373150, 2023). "N-myc downstream-regulated gene 2 (NDRG2), previously known as a tumor suppressor molecule, is involved in cell differentiation and stress-associated events." (PMID 37082656, 2023). "Compared with normal tissues, NDRG1 expression was higher, whereas NDRG2 expression was lower in tumor tissues (P <0.001)." (PMID 35795037, 2022). "This review aims to assist the research design regarding NDRG2 function as an adaptor protein and suggests NDRG2 as a molecular target to inhibit tumor metastasis and improve the prognosis in tumor patients." (PMID 36012631, 2022). "N-myc downstream-regulated gene 2 (NDRG2) is a positive regulator of apoptosis that increases tumor sensitivity to anticancer drugs, delays tumor progression and inhibits metastasis." (PMID 35991578, 2022). "In this review, we aim to provide useful information for tumor control studies by summarizing clinicopathological properties in various tumors and presenting the function of NDRG2 as a modulator of cell signaling for EMT." (PMID 36012631, 2022). "NDRG2 is frequently downregulated in cancer, and it plays an important role in the control of tumor growth and metastasis." (PMID 35888078, 2022). "Studies on NDRG2-mediated inhibition of tumor metastasis can provide useful scientific information on development of tumor therapeutics." (PMID 36012631, 2022). "The mRNA expression of NDRG1 and NDRG2 was found to be significantly different (P <0.001) in almost all tumor types, including LIHC." (PMID 35795037, 2022). "N-myc downstream-regulated gene 2 (NDRG2) is a tumor-suppressor gene that suppresses tumorigenesis and metastasis of tumors and increases sensitivity to anti-cancer drugs." (PMID 36012631, 2022). "In our study, CEACAM1 and NDRG2 were protective factors for BC prognosis (HR < 1), which is consistent with the previous consensus that they are tumor suppressors." (PMID 36685904, 2022). "N-myc downstream-regulated gene 2 (NDRG2) has been studied for its anti-proliferative and anti-metastatic effects in various tumor cell types." (PMID 33478130, 2021). "Another important tumor suppressor gene showing increased expression after Msi1 silencing is NDRG2, an n-MYC target gene, which is highly expressed in normal tissues, but undetectable in many tumors." (PMID 35011618, 2021). "In tumor cells with high MYB expression, MYB induces miR-130a expression, which inhibits the expression of tumor suppressor NDRG2 by targeting its 3'-UTR." (PMID 34876130, 2021).
tumor (continued). "It is expected that tumor treatment strategies that account for the expression pattern of NDRG2 or that regulate NDRG2 expression should increase the efficiency of tumor treatments." (PMID 34685629, 2021). "Although mechanisms that regulate NDRG2 gene expression and NDRG2-mediated improvements of tumor cell apoptosis have been presented, the molecular mechanisms of these aspects are unclear." (PMID 34685629, 2021). "N-myc downstream-regulated gene 2 (NDRG2) is a tumor suppressor gene that increases tumor sensitivity to anticancer drugs, slows tumor progression, and inhibits metastasis." (PMID 34685629, 2021). "Downregulated NDRG2 expression is closely related to poor prognoses, such as a reduction in overall survival and disease-free survival rates in tumor patients." (PMID 34685629, 2021). "Overexpressed NDRG2 inhibits tumor cell proliferation and invasion/metastasis and sensitizes tumor cells to anticancer therapy by enhancing apoptosis." (PMID 34685629, 2021). "NDRG4 and NDRG2 have also been regarded to exhibit the tumor suppressive function by inhibiting cell proliferation, migration, invasion, and metastasis in different types of cancer, such as glioblastoma and breast cancer." (PMID 33435156, 2021). "Altogether, NDRG2 is an important prognostic marker that controls various cellular physiological pathways involved in tumor aggressiveness." (PMID 34685629, 2021). "In this review, we summarize the antitumor function of NDRG2 as a tumor suppressor gene and the function of NDRG2 in relation to apoptosis in various physiological environments as a prognostic tumor marker." (PMID 34685629, 2021). "Supporting the biological significance, the reciprocal relationship between NDRG2 and ASCT2 were observed in multiple types of tumor tissues, and associated with tumor malignancy." (PMID 33162818, 2020). "Albeit the reported tumor suppressive role of NDRG2 in KIRC, the vast majority of splice variants stemmed from NDRG2 were negatively associated with the OS of KIRC." (PMID 32047561, 2020). "Previously, N-myc downstream-regulated gene 2 (NDRG2) serves as a tumor suppressor for many cancers." (PMID 32345304, 2020). "While NDRG3 shares a high similarity to NDRG2 in terms of amino acid sequence and structure, NDRG3 exhibited remarkable structural differences in a flexible loop corresponding to helix α6 of NDRG2 that is responsible for tumor suppression." (PMID 31935861, 2020). "NDRG2 is considered to be a tumor suppressor which contributes to not only hormone, ion, fluid metabolism and other cellular metabolic processes, but also stress responses, like those under hypoxic environments and lipid toxicity." (PMID 32345304, 2020). "Here, we report that N-myc downstream regulated gene 2 (NDRG2), a known tumor suppressor, is required to facilitate astroglial glutamate uptake and protect the brain from glutamate excitotoxicity after ischemia." (PMID 31250377, 2020). "Luciferase reporter and ChIP assays were used to determine the roles of Akt and c-Myc in mediating NDRG2-dependent regulation of ASCT2 in in both tumor and NDRG2-knockout MEF cells." (PMID 33162818, 2020). "This is supported by the fact that upregulation of a NDRG3 paralogous, NDRG2, suppresses tumor invasion by inhibiting the matrix metalloproteinases MMP-9 and MMP-2." (PMID 33175867, 2020). "N-Myc downstream-regulated gene 2 (NDRG2) plays an important role in tumor suppression in several cancers or cancer cell lines." (PMID 31121982, 2019). "The results of immunohistochemistry staining showed that the number of LDHA and Ki67 positive cells decreased significantly in tumor from nude mice injected with NDRG2-overexpressing HepG2 cells compared with the control groups." (PMID 31523182, 2019). "As expected, gemcitabine inhibited tumor growth in vivo, and NDRG2 knockdown partly recovered the malignant tumor growth and proliferation in nude mice that was suppressed by gemcitabine." (PMID 31523182, 2019).
tumor (continued). "We previously reported that NDRG2 is widely expressed in many normal tissues and is decreased in many types of tumor tissues 6, 26, 32-35." (PMID 31523182, 2019). "In this study, we investigated the molecular mechanism of NDRG2 function, as a kind of tumor suppressive gene, to overcome the low chemosensitivity of tumor cells." (PMID 31121982, 2019). "NDRG2 expression is positively correlated with tumor differentiation but negatively correlated with metastasis and TNM classification of malignant tumors (TNM) stage." (PMID 31121982, 2019). "By 4th week, mice injected with NDRG2-overexpressing HepG2 cells showed a statistically significant decrease in average tumor weight compared with the control groups." (PMID 31523182, 2019). "N-Myc downstream-regulated gene 2 (NDRG2) was characterized as a tumor suppressor, inducing anti-metastatic and anti-proliferative effects in several tumor cells." (PMID 31121982, 2019). "The mice injected with NDRG2-overexpressing HepG2 cells developed tumor slowly than the control groups." (PMID 31523182, 2019). "NDRG2 exerts its tumor suppressor function by influencing cancer cell proliferation and metabolism and suppressing angiogenesis." (PMID 29445150, 2018). "Increasing evidence has emerged to suggest that N-myc downstream-regulated gene 2 (NDRG2) dysregulation participates in a number of tumor biological processes." (PMID 30206227, 2018). "NDRG2, which strongly influences cell-cycle arrest, metabolic reprogramming, senescence and apoptosis, is known as a pleiotropic tumor suppressor in several malignancies." (PMID 30206227, 2018). "Throughout the course of 4 weeks, tumor volume was monitored with a caliper, and the group with NDRG2 silencing displayed significantly larger tumors than did the control mice." (PMID 30206227, 2018). "Our findings provide insights into the function of NDRG2 as a tumor suppressor and suggest that it provides a molecular target for clinical tumor therapies." (PMID 29348517, 2018). "When the experiment ended, the xenograft tumors were isolated, and the weights were measured; this assay again showed an increased tumor size and weight in mice with NDRG2 downregulation compared with control mice." (PMID 30206227, 2018). "Narrowing the tumor-promoting effect coming from BM-derived cells down to TAMs, the authors then performed tumor growth studies co-injecting tumor cells with NDRG2-KO or -WT TAMs." (PMID 29463798, 2018). "Our previous data showed that N-myc downstream-regulated gene 2 (NDRG2) was a candidate tumor suppressor in several kinds of cancers." (PMID 29445150, 2018). "N-Myc downstream-regulated gene 2 (NDRG2) has been reported to be tumor suppressor that is downregulated in aggressive tumor tissues and associated with the progression and prognosis of diverse cancers." (PMID 29348517, 2018). "The present study focused on tumor cell sensitivity to the anti-cancer drug, cisplatin, and how this was affected by NDRG2 expression." (PMID 29348517, 2018). "TNBC HCC1806 tumor xenografts with NDRG2 knockdowns showed marked tumor reduction after doxorubicin treatment as compared to controls." (PMID 28418843, 2017). "NDRG2 has been shown to be downregulated during tumor progression, and it has been postulated that NDRG2 inhibits the metastasis of HCC71–73." (PMID 29067165, 2017). "While tumor promoting genes such as AGR2 were downregulated, known tumor suppressor genes like NDRG2 and DAPK1 were upregulated 4.3- and 4.6-fold, respectively." (PMID 28231808, 2017).
tumor (continued). "NDRG2 is a relevant biomarker for predicting aggressive behavior, tumor recurrence and overall patient survival, independently or in combination with other factors, such as CD24, phospho-STAT3, and HOXD1." (PMID 26506239, 2016). "Through GSK-3β activation, NDRG2 promotes cell density-regulated E-cadherin expression and exerts anti-tumor effects." (PMID 26506239, 2016). "NDRG2 levels are positively correlated with tumor differentiation but negatively correlated with lymph node metastasis and TNM stage." (PMID 26506239, 2016). "Although NDRG4 shares about 60% amino acid sequence homology with NDRG2, different from the widely tumor suppressive role of NDRG2, NDRG4 has been considered to be expressed mainly in brain and heart, and take part in the development of these organs." (PMID 26515606, 2016). "The anti-tumor effects of NDRG2 have been demonstrated to be closely related to the promotion of apoptosis." (PMID 26506239, 2016). "Based on subtype classified tumor (n = 45) and adjacent normal tissues (n = 17) we examined NDRG2 mRNA expression and CpG-hypermethylation, whose significance was further validated by independent data sets from The Cancer Genome Atlas (TCGA)." (PMID 27400234, 2016). "The attenuation of TCF/β-catenin signaling by NDRG2 contributes to the maintenance of healthy tissues and the suppression of tumor metastasis." (PMID 26506239, 2016). "NDRG2 methylation and down-regulated NDRG2 are negatively related to depth of tumor invasion, Borrmann classification and TNM stage." (PMID 26506239, 2016). "NDRG2 antagonizes TGFβ1-mediated tumor cell invasion by down-regulating the expression of matrix metalloproteinase 2 (MMP2) and laminin 332 pathways, with concomitant suppression of Rho GTPase activity." (PMID 26506239, 2016). "We showed for the first time that the N-myc downstream regulated gene 1 (NDRG1) and NDRG2, known as tumor suppressor genes, are negatively regulated by LCN2 in CCA cells." (PMID 27782193, 2016). "NDRG2 has been suggested to be a tumor suppressor and cell stress-related gene that is involved in cellular metabolic processes, such as hormone, ion, and fluid metabolism, and in stress responses, such as those to hypoxia and lipotoxicity." (PMID 26506239, 2016). "N-Myc downstream-regulated gene 2 (NDRG2) protein is a tumor suppressor that inhibits cancer growth, metastasis and invasion." (PMID 27072586, 2016). "The down-regulation of NDRG2 expression is negatively associated with TNM stage, tumor magnitude, nuclear grade, Fuhrman's grade and tumor invasion." (PMID 26506239, 2016). "Accumulating evidence then suggested that NDRG2 played a tumor suppressor role in various human malignancies." (PMID 25749388, 2015). "By 4th week, mice injected with NDRG2-overexpressing HCT116 or HT-29 cells showed a statistically significant decrease in average tumor volume compared with the control groups." (PMID 26317652, 2015). "First, down-regulation of Ndrg2 expression is frequently observed in primary tumors and tumor cell lines." (PMID 25823664, 2015). "In this study, we discovered that tumor suppressor NDRG2 participates in tumor metabolism, especially in glycolysis and glutaminolysis." (PMID 26317652, 2015). "Our subsequent study confirmed that NDRG2 inhibited c-Myc expression and c-Myc mediated tumor glycolysis and glutaminolysis reprogramming." (PMID 26317652, 2015). "The loss of NDRG2 expression in cancer cells, including ATL and OSCC cells, induces constitutive activation of the NF-κB pathway, thereby contributing to tumor development." (PMID 26269411, 2015). "Together, the data implicate that NDRG2 acts as the tumor suppressor gene and participates in the inhibition of glycolysis and glutaminolysis by repression of c-Myc expression in cancer cells." (PMID 26317652, 2015). "Identification of the detailed molecular mechanism of NDRG2 will lead to remarkable progress in the understanding of tumor pathogenesis." (PMID 26269411, 2015).